USP22 (ubiquitin specific peptidase 22)
Diseases named in the same sentence as USP22 in open-access papers (continued):
Sharing a sentence is not in itself a finding about the gene and the disease.
breast carcinoma (37 papers, 2017 to 2025). "It is highly expressed in breast cancer samples compared to benign breast tissue, and high expression of USP22 is significantly associated with poorer overall survival in breast cancer." (PMID 40229280, 2025). "USP22 strengthens the tumorigenic activity of breast cancer cells by promoting c-Myc (a CSC-associated transcription factor) stabilization." (PMID 38517383, 2024). "We monitored mammary tumor formation in MMTV-NIC mice bearing only the endogenous allele of Usp22 (Usp22+/+) or bearing one (Usp22OE/+) or two (Usp22OE/OE) copies of the Usp22 OE transgene in addition to the endogenous allele." (PMID 38236941, 2024). "Additional studies using different, non-MMTV transgene mouse models are needed to determine the impact of Usp22 loss on these factors in mammary tumors and to define the mechanisms underlying such effects." (PMID 38236941, 2024). "Conversely, loss of USP22 expression resulted in a significant increase in FoxM1 ubiquitination in both mouse 4T1 and patient-derived breast cancer cells." (PMID 37398311, 2023). "To investigate the consequences of Usp22 loss in HER2-driven mammary carcinomas, we utilized a transgenic mouse model in which the gene encoding HER2 (Erbb2) was expressed under the mammary-specific MMTV promoter (MMTV-Erbb2)." (PMID 34007022, 2021). "Consistent with previous work in other breast cancer cell lines, loss of USP22 dramatically impaired tumorigenicity of HER2-driven mammary carcinoma cells both in vivo and in vitro." (PMID 34007022, 2021). "Intriguingly, we were able to demonstrate that HSP90AB1 levels are reduced upon USP22 loss in both colorectal and breast cancer cells in vitro." (PMID 31801945, 2019). "Indeed, ectopic ITGB1 expression partially rescued tumor sphere formation from in both mouse 4T1 and patient-derived L2G+ TN1 USP22-deficient breast cancer cells." (PMID 37398311, 2023). "HSP90AB1, a target gene of USP22, is associated with poor prognosis in breast cancer." (PMID 35935969, 2022). "USP22-mediated deubiquitination of c-MYC is closely associated with breast cancer progression." (PMID 35935969, 2022). "Loss of USP22 results in increased sensitivity of breast cancer to HSP90 inhibitors." (PMID 35935969, 2022). "Furthermore, USP22 overexpression was associated with breast cancer lymph node metastasis and recurrence, and was a pointer of poor prognosis." (PMID 29934362, 2018). "We further unbiasedly analyzed the USP22 and B2M transcripts in breast cancer cell lines listed in Cancer Cell Line Encyclopedia (CCLE)." (PMID 41252204, 2025). "In breast cancer cells, USP22 deubiquitinates and stabilises c‐Myc to promote breast cancer progression." (PMID 39661501, 2024). "In breast cancer, the deubiquitinating enzyme USP22 interacts with CD73, inhibiting CD73 ubiquitination and proteasomal degradation, thereby stabilizing its protein levels." (PMID 39223632, 2024). "Our discovery that genetic USP22 deletion hindered breast cancer stem cell self-renewal and inhibited their lung metastasis provides a rationale for USP22 targeting in anticancer therapy." (PMID 37398311, 2023). "In this study, we present evidence that USP22 is highly expressed in breast cancer stem cells and required for both breast cancer initiation and metastasis." (PMID 37398311, 2023). "Collectively, these results indicate that USP22 promotes breast cancer metastasis at least partially, through promoting FoxM1-mediated integrin b1 expression." (PMID 37398311, 2023). "We next set out to determine the effects of USP22 pharmacological inhibition on breast cancer stem cell self-renewal." (PMID 37398311, 2023). "Integrin β1 reconstitution partially rescued USP22-null breast cancer stemness and their metastasis." (PMID 37398311, 2023).
breast carcinoma (continued). "To further determine the critical roles of the USP22-FoxM1-integrin b1 in breast cancer pathogenesis, we utilize the immunohistochemistry staining determined the expression of USP22, FoxM1, and integrin b1 protein in human breast cancer tissue microarray." (PMID 37398311, 2023). "We then utilized the lung metastasis model to further illustrate the role of USP22-FoxM1-integrin b1 pathway in breast cancer tumorigenesis in BALB/c mice." (PMID 37398311, 2023). "Our studies here define the USP22-FoxM1-integrin b1 axis as critical regulatory node in control of breast cancer stem cell self-renewal, tumor initiation and metastasis." (PMID 37398311, 2023). "Our previously study has demonstrated that USP22 maintains estrogen receptor α (ERα) stability through its deubiquitination activity to co-activate ERα-mediated transactivation in breast cancer cells." (PMID 36906615, 2023). "Consistent with this, we observed that ectopic expression of FoxM1 largely restored the tumor sphere formation ability of USP22-deficent breast cancer cells." (PMID 37398311, 2023). "For instance, in breast carcinoma USP22 and USP36 are known to regulate the cellular turnover of c-MYC." (PMID 36985413, 2023). "Our study defines the USP22-FoxM-integrin b1 axis as a previously unappreciated pathway in breast cancer initiation and metastasis, that can be therapeutically targeted to antagonize invasive breast cancers." (PMID 37398311, 2023). "In fact, pharmacological USP22 inhibition dramatically reduced the frequency of breast cancer stem cells and attenuated both mouse and human invasive breast cancer lung metastasis." (PMID 37398311, 2023). "FoxM1 has been identified as an integrin β1 transcription factor thereby promoting breast cancer progression 27, implying a possibility that USP22 controls breast cancer cell ITGB1 expression through FoxMl stabilization." (PMID 37398311, 2023). "The endogenous interaction between USP22 and FoxM1 in patient-derived breast cancer L2G+ TN1 cells was further validated." (PMID 37398311, 2023). "To decipher the USP22 functions in generating and/or maintaining breast cancer cell stemness, we generated USP22 targeted deletion in mouse 4T1 and human breast cancer-derived L2G+ TN1 cells by a CRISPR-Cas9 approach." (PMID 37398311, 2023). "USP22 promotes the deubiquitination of c-MYC in breast cancer cells, resulting in increased levels of c-MYC." (PMID 35408841, 2022). "USP22 inhibits HER2-mediated breast cancer aggressiveness via reducing the unfolded protein response." (PMID 35692754, 2022). "USP22 promotes the deubiquitination of c-MYC in breast cancer cells, resulting in an increase in c-MYC level." (PMID 35935969, 2022). "For example, USP22 can promote breast cancer aggressiveness by stabilizing the proto-oncogene c-Myc to reprogram cellular metabolism and stimulate mRNA and protein synthesis." (PMID 34007022, 2021). "Subsequent studies have shown that Usp22 is overexpressed in many cancer types, including breast cancer, lung cancer, and pancreatic cancer." (PMID 34503086, 2021). "To date, investigations into the function of USP22 in breast cancer have been solely limited to in vitro studies and immunohistochemical staining of tumor samples and did not specifically investigate its relevance in HER2+-BC." (PMID 34007022, 2021). "USP22 deubiquitinates and stabilizes ERα, enhancing ERα-induced transactivation in breast cancer cells." (PMID 34575114, 2021). "Mechanistically, USP22 enhances cell migration and tumorigenesis in breast cancer partially through its deubiquitination and stabilization of c-Myc." (PMID 34575114, 2021). "A recent report showed that USP22, a constitutive nuclear deubiquitinase, can promote ERα stability by deubiquitinating ERα in the nucleus of breast cancer cells." (PMID 34131114, 2021).
breast carcinoma (continued). "In breast cancer cell lines, USP22 reduction enhances the inhibitory effects on proliferation of ERα antagonist ICI 182,780 and tamoxifen by increasing cell sensitivity to endocrine therapy." (PMID 34575114, 2021). "Overexpression of USP22 has been frequently observed in patients with invasive breast cancer, relating to fast progression and adverse outcomes in breast cancer." (PMID 34575114, 2021). "The role of Usp22 in breast cancer has mostly been analyzed in cell lines, and a thorough analysis of Usp22 in mouse models of breast cancer is currently lacking." (PMID 34503086, 2021). "One of these is with the oncogene c-Myc where USP22 has been reported to function as a DUB to increase c-Myc stability in breast cancer cell lines with implications for the progression of this malignancy." (PMID 33233707, 2020). "USP22 promotes deubiquitination of c-MYC in breast cancer cells, resulting in increased levels of c-MYC." (PMID 32268558, 2020). "Overexpression of USP22 stimulates tumorigenic activity in breast cancer cells and is closely correlated with breast cancer progression." (PMID 32268558, 2020). "In colorectal and mammary cancer, the Ubiquitin-Specific Protease 22 (USP22) enhances the expression of HSP90AB1 and promotes resistance to HSP90 inhibition." (PMID 32046099, 2020). "Based on its function in deubiquitinating H2B and oncogenic proteins, increased USP22 levels were reported to accelerate colorectal and breast cancer development and progression." (PMID 31801945, 2019). "To investigate the function of USP22 in cancer development and progression, we sought to detect common USP22-dependent molecular mechanisms in human colorectal and breast cancer cell lines." (PMID 31801945, 2019). "The downregulation of HSP90AB1 was confirmed at the protein level in these cell lines as well as in colorectal and mammary tumors in mice with tissue-specific Usp22 deletions." (PMID 31801945, 2019). "Several studies have shown that reduced USP22 expression correlates with a G1 accumulation in normal human fibroblasts and in lung, colorectal and breast cancer cell lines." (PMID 29210986, 2017). "USP22 functions as a de novo FoxM1-specific deubiquitinase in breast cancer cells." (PMID 37398311, 2023). "Likewise, the impaired ability in colony formation of 4T1 breast cancer cells by USP22 depletion was largely rescued by exogenous FoxM1 expression." (PMID 37398311, 2023). "Indeed, western blotting analysis revealed a significant reduction in the protein expression of FoxM1, a critical transcription factor for ITGB1 expression 27, in USP22-null breast cancer cells." (PMID 37398311, 2023). "Importantly, we detected a significant reduction in CD44+ breast cancer cells in the S02 treat group, implying that USP22 pharmacological inhibition attenuates either the breast cancer stem cell self-renewal or their survival." (PMID 37398311, 2023). "Indeed, treatment of USP22-null cells with the proteasome inhibitor MG132 largely restored FoxM1 expression to a level comparable to that in WT breast cancer cells." (PMID 37398311, 2023). "Further characterization by IHC staining show that the levels of USP22, FoxM1 and integrin b1 protein expression by USP22i-S02 treatment, which consequently inhibited the breast cancer cell growth because the percentage of Ki-67+ proliferative cells was dramatically decreased." (PMID 37398311, 2023). "Our study defines a previously unknown USP22-FoxM1-integrin b1 pathway critically important for both mouse and human breast cancer stem cell self-renewal." (PMID 37398311, 2023). "Therefore, pharmacological inhibition of USP22 achieves represents a potentially efficacious treatment for breast cancer and metastasis." (PMID 37398311, 2023). "Therefore, USP22 controls breast cancer stem cell self-renewal through protecting FoxM1 from ubiquitination-mediated proteasomal degradation to enhance ITGB1 transcription." (PMID 37398311, 2023).
breast carcinoma (continued). "Indeed, the tumor sphere formation from both patient derived L2G+ TN1 and mouse 4T1 breast cancer cells was largely impaired by USP22 CRISPR deletion, which was further confirmed by an in vitro extremely limiting dilution assay." (PMID 37398311, 2023). "Positive correlation of USP22, FoxM1 and integrin b1 in human breast cancer." (PMID 37398311, 2023). "USP22 is required for the tumorigenicity of breast cancer stem cells." (PMID 37398311, 2023). "We then determined whether USP22 exerted a driving role in breast cancer metastasis by intravenously injection of 4T1 USP22-null or its control WT cells into BALB/c mice." (PMID 37398311, 2023). "Surprisingly, in contrast to the fact that five out of eight mice implanted with 102 WT 4T1 cells developed cancer three months after implantation, none of the eight mice received with USP22-deficient 4T1 cells developed breast cancer." (PMID 37398311, 2023). "USP22 may be one of the major factors in breast cancer progression and a potential therapeutic target for endocrine resistance." (PMID 35935969, 2022). "USP22 plays an important role in the proliferation, differentiation, and cycle of breast cancer." (PMID 35935969, 2022). "Furthermore, overexpression of USP22 stimulates breast cancer cell proliferation and aggregation and increases c-MYC tumorigenic activity." (PMID 35935969, 2022). "In breast cancer cells, USP22 positively regulated ERα expression via maintaining its stability." (PMID 35692754, 2022). "In addition, USP22 is identified as a biomarker in ER+ breast cancer by enhancing tumor growth via stabilization of ERα." (PMID 34575114, 2021). "As a result, USP22 increases breast cancer resistance to ERα antagonists." (PMID 34575114, 2021). "Indeed, analysis of HER2+-BC patients within the TCGA breast cancer cohort confirms that patients with tumors displaying high USP22 expression show a particularly poor prognosis." (PMID 34007022, 2021). "Although the role of SETD5 in breast cancer is largely unexplored, it is possible that its upregulation by the overexpression of Usp22 may play a role in promoting aggressive cancer phenotypes." (PMID 34503086, 2021). "H2Bub1-associated DUBs USP22, USP51 and USP27X have been shown in vitro to be required for normal growth, with in vivo depletion suppressing tumour growth in a mouse xenograft model of breast cancer cells." (PMID 33233707, 2020). "In this study, we aimed to investigate the function of USP22 in colorectal and breast cancer and to detect common USP22-dependent molecular mechanisms which may be exploited for cancer treatment." (PMID 31801945, 2019). "USP22 increases the stability and tumorigenic activity of c-Myc in breast cancer cells." (PMID 31689236, 2019). "Future studies might reveal whether USP22 loss, and the subsequent reduction of HSP90 levels, will sensitize colorectal and breast cancer cells towards platinum-based therapy." (PMID 31801945, 2019). "Thus, we sought to obtain a broad overview of the transcriptome-wide consequences of USP22 depletion in various colorectal and mammary cancer cell lines in vitro." (PMID 31801945, 2019). "Furthermore, USP22 overexpression correlated with lymph node metastasis and breast cancer reoccurrence, and was an indicator of poor prognosis." (PMID 29541423, 2018). "Others have shown a role for Usp22 in regulating anti-tumor immunity through the modulation of T-regs and future studies using deletion or overexpression of Usp22 in Tregs within a mouse breast cancer model could lead to significant insights to how Usp22 overexpression affects tumorigenesis." (PMID 38236941, 2024). "Indeed, comparison analysis by western blotting and flow cytometry of integrin family members between WT and USP22-null breast cancer cells detected a dramatic reduction in integrin b1 expression by USP22 inhibition in both mouse 4T1 and patient-derived L2G+ TN1 cells." (PMID 37398311, 2023).
breast carcinoma (continued). "Interestingly, heterozygous Usp22 deletion in mammary carcinoma cells was sufficient to significantly increase disease-free survival of MMTV-Erbb2 animals (median survival: 209 days), implying that the reduction of USP22 levels is sufficient to impair the oncogenic properties of HER2+-BC." (PMID 34007022, 2021). "USP22 and USP36 regulate the cellular turnover of c-MYC in breast cancer, and c-MYC expression is stabilized by USP28 and USP37 in colon carcinoma and lung cancer, respectively." (PMID 39664521, 2024). "USP22 and Fascin regulate the transcription of ITGB1, influencing the self-renewal and metastasis of breast cancer stem cells." (PMID 39239559, 2024). "In breast cancer, the interaction between Myc and deubiquitinases (USP28 and USP22) reinforces protein stability and contributes significantly to cell proliferation." (PMID 39146353, 2024). "Other studies by this group indicated USP22 impacts stability of HSP90AB1 in prostate cancer and breast cancer cells, including HCC1954 cells." (PMID 38236941, 2024). "Similar to our observation from USP22 CRISPR KO studies, treatment of breast cancer cells 4T1 and TN1 significantly inhibited both integrin b1 and FoxM1 expression." (PMID 37398311, 2023). "USP22 positively regulates c-Myc, androgen receptor, and HIF-1α actions to promote breast cancer, prostate cancer, and HCC progression." (PMID 36906615, 2023). "Collectively, our results revealed that USP22 play an important role in breast CSC maintenance, which is critical for breast cancer initiation and metastasis." (PMID 37398311, 2023). "We also noticed that, while FoxM1 expression fully rescued integrin b1 expression both in USP22-null 4T1 and TN1 breast cancer cells, but their sphere and colony formation were only partially restored by FoxM1 re-expression." (PMID 37398311, 2023). "The large majority (10/13) of these genes were reported to play a role in the regulation of estrogen and/or progesterone response in human breast cancer (NCOA7:; NCOA3:; USP22:; MED24:; CCAR1:; CRY2:; STAT5B:; PAGR1:; TAF1:; PHB2:)." (PMID 35996163, 2022). "It is believed that imbalances of USP22, USP27X, and USP51 lead to SAGA-related breast cancer development." (PMID 34575114, 2021). "It was reported that USP22 and USP36 promote breast cancer growth targeting the oncogenic protein, c-Myc." (PMID 34575114, 2021). "GRP78 was found that to be stabilized by USP22 and suppresses UPR-induced apoptosis in HER2-positive human breast cancer cell lines SKBr3 and HCC1954." (PMID 34943954, 2021). "We recently reported a SAGA-related role for USP22 in supporting the protein chaperoning system by transcriptionally activating the expression of members of the HSP90 family in colorectal and breast cancer cells." (PMID 34007022, 2021). "Depletion of USP22, USP51, or USP27X inhibits breast cancer growth partly through downregulation of H2Bub1." (PMID 34575114, 2021). "In the present study, we leveraged human cell lines and genetic mouse models to investigate the role of USP22 in HER2-driven breast cancer (HER2+-BC) and demonstrate for the first time that USP22 is required for the tumorigenic properties in murine and human HER2+-BC models." (PMID 34007022, 2021). "Interestingly, USP22-deficient cells displayed a high dependence on HSP90AB1 expression and diminishing HSP90 activity further using the HSP90 inhibitor Ganetespib resulted in increased therapeutic vulnerability in both colorectal and breast cancer cells in vitro." (PMID 31801945, 2019). "Consistent with our observations in human breast cancers, IHC staining of EZH2, USP22, β2M, and CD8+ in serial tissue sections in human prostate and colon cancer tissue microarrays confirmed the increased expression of USP22 and EZH2 in tumors compared with benign tissues." (PMID 41252204, 2025).